PIK3C2A (phosphatidylinositol-4-phosphate 3-kinase catalytic subunit type 2 alpha)
Diseases named in the same sentence as PIK3C2A in open-access papers (continued):
Sharing a sentence is not in itself a finding about the gene and the disease.
cancer (22 papers, 2008 to 2025). A tumor composed of atypical neoplastic, often pleomorphic cells that invade other tissues. "Recent studies have begun to elucidate the unique roles of class II PI3Ks in cancer; for instance, PIK3C2A has been implicated in sustaining mitogenic signaling and cell division, while PIK3C2G is linked to cytoskeletal reorganization and membrane trafficking." (PMID 41362647, 2025). "In cancer, PIK3C2A has been associated with the dysregulation of the phosphoinositide 3-kinase (PI3K)/AKT/mTOR pathway, which is frequently observed in various cancer types." (PMID 38067251, 2023). "The correlation of PIK3C2A expression with infiltrating immune cells in various types of cancer was analyzed using the TIMER, TCGA, and GEPIA databases." (PMID 37063922, 2023). "PIK3C2A was also found to be correlated with the prognosis of numerous cancers, and predicted favorable OS, DFS, and PFS in KIRC." (PMID 37063922, 2023). "To date, no comprehensive study has been conducted to evaluate the role of PIK3C2A in cancer, and characterize its prognostic landscape." (PMID 37063922, 2023). "Overexpression of the PI3K-C2α encoding gene, PIK3C2A, was found in an MCF7 cancer stem-cell side population, correlating with increased tumorigenesis in mouse models." (PMID 34298731, 2021). "As an example, TAOK1, an understudied kinase, shows high co-expression with PIK3C2A in 17,382 normal samples and 1376 cancer samples in the Genotype-Tissue Expression project (GTEx, version 8) and the Cancer Dependency Portal (DepMap, 20Q4), respectively." (PMID 34537014, 2021). "For example, a fusion between the PTEN (phosphatase and tensin homolog) and the 3′ UTR of the PIK3C2A (phosphatidylinositol-4-phosphate 3-kinase, catalytic subunit type 2 alpha) genes resulted in the down regulation of PTEN > 2-fold in our cancer samples." (PMID 28851357, 2017). "Several inhibitors of this pathway, such as rapamycin and its derivatives which inhibit mTOR (FRAP1) and the PI3K (PIK3C2A) inhibitor wortmannin, are in fact now being actively evaluated in clinical trials for other cancers." (PMID 18538015, 2008). "Therefore, several data sources were screened to fully comprehend the functions of PIK3C2A in cancer." (PMID 37063922, 2023). "It was found that PIK3C2A influenced immunocyte infiltration in many cancers, particularly KIRC." (PMID 37063922, 2023). "Additionally, the interrelation between PIK3C2A and the biomarkers of immunocytes suggested that PIK3C2A was involved in the modulation of cancer immunity in KIRC." (PMID 37063922, 2023). "Furthermore, aberrant PIK3C2A expression can influence the biological activity of cancer cells." (PMID 37063922, 2023). "Further research is warranted to establish whether PIK3C2A has dual effects on cancer immunity." (PMID 37063922, 2023). "Therefore, we speculate that PIK3C2A can transform Tregs into proinflammation cells which have anti-cancer-promoting utility by decreasing the expression of FOXP3." (PMID 37063922, 2023). "In addition, mutations in PIK3C2A reported in cancer samples are distributed evenly across the protein and do not recurrently affect specific residues, suggesting these are passenger events." (PMID 25159823, 2014). "However, the roles of PIK3C2A in the progression of cancer remain unknown understood." (PMID 37063922, 2023). "However, the role of PIK3C2A in cancer prognosis and progression remains unknown." (PMID 37063922, 2023). "While there is clear evidence that PIK3C2A scaffold function acts as a tumor suppressor, there is a lack of knowledge concerning its kinase function in cancer progression." (PMID 30884740, 2019). "The fact that Pik3c2a is up-regulated in Lin-/VEGF-R2+ D-EPCs is supported by studies that demonstrated an inhibitory effect of up-regulated Pik3c2a on epithelial and cancer cell proliferation, migration and colony formation illustrating the observed dysfunction of Lin-/VEGF-R2+ D-EPCs." (PMID 29995913, 2018).
cancer (continued). "Even though four (PIK3C2A, JUN, FNBP1, ITPR1) of our peripheral biomarkers have been implicated in cancer pathophysiology, none of the PBMC biomarkers were differentially expressed between tumor types (among all subjects, or within cases or controls alone)." (PMID 21884629, 2011). "While PIK3C2A function is not as well understood as those of the class I PI3 kinases, it generally functions in vesicular trafficking and intracellular trafficking, with several studies indicating a role in cancer." (PMID 35269443, 2022).
tumor (18 papers, 2011 to 2024). "The establishment of a subcutaneous xenograft tumor model in nude mice demonstrated that the loss of function of circ-PIK3C2A efficiently reduced tumor load in vivo and prolonged the survival duration of tumor-bearing animals." (PMID 35883576, 2022). "Tumor two harbored a mutation in PIK3C2A, encoding the class II PI3K-C2α enzymes; the role of this enzyme in cell signaling and cell survival has been debated, but the most recent evidence indicates that it does not activate AKT." (PMID 25159823, 2014). "This, in turn, allows miR-133a to suppress the PAM signaling pathway in tumor cells by reducing the expression of EGFR and PIK3C2A targets, ultimately resulting in decreased growth and development of tumor cells." (PMID 38504785, 2024). "According to the results, PIK3C2A expression was negatively correlated with tumor proliferation signature and DNA replication pathways (Spearman’s correlation value = -0.30 and -0.15, respectively, P<0.001)." (PMID 37063922, 2023). "Firstly, we assessed the relationship between PIK3C2A and tumor-related signal pathways using ssGSEA." (PMID 37063922, 2023). "The results demonstrated lower PIK3C2A protein levels in KIRC tissues than in neighboring non-tumor kidney tissues." (PMID 37063922, 2023). "According to the Human Protein Atlas database, the PIK3C2A protein level was significantly lower in KIRC tissues compared with adjacent non-tumor kidney tissues." (PMID 37063922, 2023). "After adjustment for tumor purity, M1 and M2 macrophage markers exhibited strong correlations with PIK3C2A expression." (PMID 37063922, 2023). "As such, the present investigation seeks to elucidate the role and mechanism of PIK3C2A in tumor progression." (PMID 37063922, 2023). "In this work, the relationships between PIK3C2A and tumor immunocyte infiltration were investigated by relying on the TIMER database." (PMID 37063922, 2023). "Circ-PIK3C2A expression increased the proliferation, invasion, and creation of tumor cells; deletion of circ-PIK3C2A function had the exact opposite effect on the tumor cells’ growth and development." (PMID 35883576, 2022). "Exonic deletions were detected in the PPP2R5A, FHIT, LRP1B, and OPCML tumor suppressor genes, as well as in genes implicated in cellular proliferation (CCNB1, ANAPC5, PIK3C2A) and DNA repair (SMARCA5)." (PMID 30836646, 2019). "In human endothelial cells, PIK3C2A plays an important role in vessel formation and integrity contributing to the early embryonic lethality and impaired tumor angiogenesis in the Pik3c2a mutant mice." (PMID 30884740, 2019). "These experiments illustrated that miR-124 plays a tumor suppressor role in HCC cells by targeting PIK3C2A and CD151." (PMID 27270320, 2016). "In HCC cell lines QGY- 7703 and SMMC-7721, and normal hepatic cell line HL-7702, miR-124 plays a tumor suppressor role by targeting PIK3C2A and CD151." (PMID 27270320, 2016). "PIK3C2A expression in tumor cells was dramatically downregulated in the right KIRC tissue (KIRC1)." (PMID 37063922, 2023). "In conclusion, PIK3C2A participates in the recruitment and modulation of immunocyte infiltration in KIRC, suggesting that adjusting PIK3C2A expression may be a useful therapeutic strategy to restore an effective anti-tumor immune response." (PMID 37063922, 2023). "As a result, we selected KIRC to further investigate the role of PIK3C2A in tumor progression." (PMID 37063922, 2023). "These add to the evidence that PIK3C2A is strongly linked to immune infiltration in KIRC and may play a dualistic role in tumor immune responses." (PMID 37063922, 2023). "Gene expression levels measured relative to the adjacent normal cortex sample revealed numerous oncogenic driver genes with >2-fold higher expression in the tumour and clone samples, including genes encoding AURKA/B, CDK4/6, FGFR1, AKT1/2, MTOR, MET, PIK3C2A, WNT5A, SFRP4, and MYC." (PMID 30736342, 2019).
tumor (continued). "Consistent with this, this study reported that tumour onset was delayed in a transgenic mouse model of mammary carcinogenesis upon crossing with heterozygous PIK3C2A+/− mice but this was then followed by a progressively increased rate of tumour formation in these mice." (PMID 31752944, 2019). "Furthermore, breast cancer development in NeuT mice which are heterozygous for Pik3c2a has a biphasic propagation with an initial delay in tumor onset followed by the emergence of fast-growing clones." (PMID 30884740, 2019). "After subcutaneous injection of Lewis lung carcinoma (LLC) or B16-BL6 melanoma tumors, Pik3c2a endothelial-restricted knock-out mice had reduced tumor volumes/weights compared to control, suggesting that the in vivo pro-angiogenetic function of PI3K-C2α is required for tumor growth and maintenance." (PMID 23658859, 2013). "Furthermore, the correlation of PIK3C2A expression with tumor immunity was investigated in KIRC." (PMID 37063922, 2023). "Consequently, the relationship between PIK3C2A, ubiquitin, insulin, and the mTOR signaling pathway may be an important modulator of tumor immunity." (PMID 37063922, 2023). "PIK3C2A protein expression level was further evaluated in eight pairs of KIRC and neighboring non-tumor kidney tissues by western blot." (PMID 37063922, 2023). "PIK3C2A and PIK3C2B were suggested to play a role in tumor progression." (PMID 34681622, 2021). "Two DEGs (PIK3C2A and RB1CC1) that closely related to autophagy initiation were significantly inhibited, suggesting that ZBTB38 downregulation also blocked autophagy, an important mechanism that protects the cells from programmed cell death, thus accelerating apoptosis of tumor cells." (PMID 30697495, 2019). "First, PIK3C2A was not related to tumor purity in KIRC, indicating that PIK3C2A was both expressed in malignant cells and the tumor microenvironment." (PMID 37063922, 2023).
PIK3C2A also shares sentences with these, for which no sentence is quoted: bipolar disorder (2 papers); depression (2); infection (2); kidney failure (2); lung adenocarcinoma (2); Obesity (2); Renal cyst (2); angina (1); atherosclerosis (1); bladder urothelial carcinoma (1); breast tumor (1); cardiac hypertrophy (1); cardiovascular diseases (1); cyst (1); developmental delay (1); Duchenne muscular dystrophy (1); glioma (1); glomerulosclerosis (1); Glucose intolerance (1); head and neck squamous cell carcinoma (1); Hypercholesterolemia (1); Hyperglycemia (1); Insulin resistance (1); intellectual disabilities (1); Joubert syndrome (1); kidney chromophobe (1); lung squamous cell carcinoma (1); lymphoma (1); Meckel syndrome (1); mental disorder (1).
A further 6 diseases each share a sentence with PIK3C2A in 1 paper.